G6PD (glucose-6-phosphate dehydrogenase)
Diseases named in the same sentence as G6PD in open-access papers (continued):
Sharing a sentence is not in itself a finding about the gene and the disease.
cystic fibrosis (9 papers, 2005 to 2025). Autosomal recessive disorder caused by pathogenic variants in the CFTR gene (cystic fibrosis transmembrane conductance regulator), which encodes a chloride and bicarbonate channel expressed in epithelial cells, and follow the diagnosis criteria. "Thecurrent study aimed to screen neonates for Congenital Hypothyroidism, Cystic Fibrosis, G6PD deficiency, and Profound Biotinidasedeficiency to expedite diagnosis and subsequent treatment and to facilitate the prevention of adverse outcomes." (PMID 37701517, 2022). "Two patients had sickle cell trait, two had β-thalassemia trait, one had CFTR gene mutation (cystic fibrosis heterozygosity), and four females had G6PD gene mutations (glucose-6-phosphatase dehydrogenase heterozygosity)." (PMID 27391121, 2016).
esophageal squamous cell carcinoma (9 papers, 2016 to 2025). Esophageal squamous cell carcinoma (ESCC) is a type of esophageal carcinoma (EC) that can affect any part of the esophagus, but is usually located in the upper or middle third. "In esophageal squamous cell carcinoma (ESCC), G6PD is an independent prognostic factor." (PMID 39859324, 2025). "DNA polymerase iota (Pol ι) activates glucose-6-phosphate dehydrogenase (G6PD) through Erk-OGT-induced O-GlcNAcylation, promoting the proliferation of esophageal squamous cell carcinoma." (PMID 39285476, 2024).
Hypertension (9 papers, 2014 to 2026). The presence of chronic increased pressure in the systemic arterial system. "Interestingly, G6PD deficiency in mice reduces angiotensin II-induced hypertension and atherosclerosis, and a loss-of-function Mediterranean G6PD (G6PDS188F) variant in rat reduces hypertension and large artery stiffness induced by feeding of HFD/obesogenic diet for 4 months." (PMID 38876306, 2024). "Another enzyme that plays an important role in the pathophysiology of hypertension is glucose-6-phosphate dehydrogenase (G6PD)." (PMID 35283964, 2021).
rheumatoid arthritis (9 papers, 2017 to 2026). A chronic, systemic autoimmune disorder characterized by inflammation in the synovial membranes and articular surfaces. "We present a case of hemolysis in a glucose-6-phosphate dehydrogenase- (G6PD-) deficient patient receiving high-dose vitamin C infusions for his rheumatoid arthritis." (PMID 29317868, 2017). "This is consistent with a previous study reporting lower levels of G6PD enzymatic activity in patients with rheumatoid arthritis and Sjögren’s syndrome, which in many cases was subclinical and of acquired origin." (PMID 37753082, 2023).
Stroke (9 papers, 2013 to 2025). Sudden impairment of blood flow to a part of the brain due to occlusion or rupture of an artery to the brain. "The risk of hemoglobin decline should be carefully monitored in G6PD‐deficient stroke patients taking aspirin." (PMID 34369077, 2021). "Co‐inheritance in SCA of alpha‐thalassaemia and glucose‐6‐phosphate dehydrogenase (G6PD) polymorphisms is reported to associate with high CBFv and/or risk of stroke." (PMID 24666344, 2014). "Whether hemoglobin decline induced by aspirin in G6PD‐deficient patients influences stroke outcomes remains unknown." (PMID 34369077, 2021). "Additionally, enzymes such as glucose-6-phosphate dehydrogenase (G6PD) are implicated in redox balance and energy homeostasis; deficiencies or dysfunctions in these enzymes can lead to metabolic disturbances manifesting as fatigue, especially in the context of stroke and its treatments." (PMID 41585085, 2025). "Our finding is in agreement with the report of Belisario et al25 who also found that G6PD deficiency did not influence stroke risk or occurrence of ischemic stroke among Brazillian children with SCA." (PMID 33938598, 2021). "Therefore, the activation of G6PD via the enhancement of HSP27 phosphorylation induced by GGA may be used to widen the therapeutic time window and to protect neural tissue against reperfusion injury, which may improve the results of stroke treatment with mechanical thrombectomy." (PMID 33557752, 2021).
tuberculosis (9 papers, 2007 to 2025). A chronic, recurrent infection caused by the bacterium Mycobacterium tuberculosis. "Other less-commonly ordered tests included stool microscopy, hepatitis C test, glucose-6-phosphate dehydrogenase test, tuberculosis sputum microscopy, liver function tests, renal function tests, glucose tests, and HIV tests." (PMID 38094983, 2023). "The other was a G6PD-deficient woman (heterozygous for the Mahidol mutation) diagnosed with HIV and tuberculosis who had received 0.25 mg/kg of primaquine and developed haemoglobinuria; its relationship to primaquine and AE outcome were unclear." (PMID 36109733, 2022).
epilepsy (8 papers, 2007 to 2025). A brain disorder characterized by episodes of abnormally increased neuronal discharge resulting in transient episodes of sensory or motor neurological dysfunction, or psychic dysfunction. "Eight out of ten patients had a concomitant condition: 3/10 (30%) had autism spectrum disorder, 2/10 (20%) had epilepsy and developmental delay, 1/10 (10%) had glucose-6-phosphate deficiency (G6PD) and developmental delay, 1/10 (10%) had language delay, and 1/10 (10%) had multiple food allergies." (PMID 40426821, 2025). "In particular, it is important to elucidate how the suppression of G6PD function modulates the baseline level of ROS and changes in ROS caused by synaptic activation, as well as the effect of G6PD inhibition on seizure generation in models of epilepsy." (PMID 38339211, 2024). "G6PD dysfunction, affecting the PPP, is implicated in neurological disorders, including epilepsy." (PMID 38339211, 2024). "Using the specific G6PD inhibitor G6PDi−1, we assessed its effects on mouse hippocampal slices, examining intracellular ROS, glucose/oxygen consumption, the NAD(P)H level and ROS production during synaptic stimulation and in the 4AP epilepsy model." (PMID 38339211, 2024).
neonatal jaundice (8 papers, 2018 to 2024). A pigmentation disease characterized by a high level of bilirubin in the blood, causing a yellowing of the skin and other tissues of a newborn infant. "G6PD plays an important role in protecting red blood cells from oxidative stress, and the most common clinical manifestations of G6PD-deficient patients are neonatal jaundice and acute hemolytic anemia." (PMID 36353116, 2022). "Neonatal jaundice (NNJ) is a major cause of preventable childhood mortality and long-term impairment especially in countries with significant prevalence of the inherited condition, glucose-6-phosphate dehydrogenase (G6PD) defect." (PMID 35239710, 2022).
pancreatic cancer (8 papers, 2019 to 2024). "G6PD knockdown prevented pancreatic cancer metastasis, highlighting the importance of G6PD-associated NADP+ generation associated with pancreatic cancer cell proliferation and metastasis." (PMID 36984785, 2023). "Metabolic classification suggests the GLUT1/ALDOB/G6PD axis as a therapeutic target in chemotherapy-resistant pancreatic cancer." (PMID 39588377, 2024). "Under various stress conditions, pancreatic cancer cells show increased de novo NADP+ synthesis through the up-regulation of G6PD to increase the efficacy of cellular antioxidant mechanisms." (PMID 36984785, 2023). "Following this, G6PD activity was determined in other pancreatic cancer cell lines with variable expression of CD133." (PMID 31740660, 2019). "In summary, we made the interesting observation that PRLR-SF signals induced via the NEK9-Hippo pathway reduce the expression of G6PD and TKT in the PPP and thereby reduce pancreatic tumor progression." (PMID 33664869, 2021). "G6PD and TKT were more highly expressed in pancreatic tumors from KPC mice than in pancreatic tissues from WT mice." (PMID 33664869, 2021). "High glucose metabolism due to GLUT1/ALDOB/G6PD axis expression promotes drug resistance in pancreatic cancer, and inhibition of the GLUT1/ALDOB/G6PD axis may serve as a target for drug resistance therapy." (PMID 38297250, 2024).
Thrombocytopenia (8 papers, 2014 to 2026). A reduction in the number of circulating thrombocytes. "Laboratory findings revealed leukopenia, thrombocytopenia, elevated unconjugated bilirubin, markedly reduced G6PD activity, and elevated creatine kinase levels." (PMID 41948394, 2026). "The hematological symptoms of HEV infection include thrombocytopenia, autoimmune hemolytic anemia, and glucose-6-phosphate dehydrogenase (G6PD) insufficiency." (PMID 39452712, 2024).
atherosclerosis (7 papers, 2016 to 2024). A disease characterized by the build-up of fatty material and calcium deposition in the arterial wall resulting in partial or complete occlusion of the arterial lumen. "Previously, we have shown that inhibiting G6PD activity or silencing G6PD expression reduces vascular tone and blood pressure, and others have shown that G6PD deficiency prevents angiotensin-induced hypertension and atherosclerosis in mice." (PMID 38876306, 2024). "Notably, in this experimental model, the lower atherosclerosis in G6PD-deficient mice cannot be attributed to the reduced bioavailability of NO since apoE–/– eNOS double knock-out mice show increased atherosclerosis." (PMID 34007401, 2021). "To investigate the relative contribution of the PPP to key monocyte and macrophage functions during atherosclerosis we used DHEA, a pharmacological inhibitor targeting glucose-6-phosphate dehydrogenase (G6PD), a rate-limiting enzyme controlling metabolic flux into this pathway." (PMID 39424804, 2024). "Finally, NO has been shown to induce the inhibition of low density lipoprotein (LDL) oxidation that is implicated in the early stages of atherosclerosis; therefore, it is not unreasonable that G6PD deficiency, causing NO depletion, may facilitate the formation of proatherogenic oxidized LDL." (PMID 34007401, 2021). "Mice lacking HO-1 are more susceptible to myocardial infarction and atherosclerosis; mice lacking NQO1 are more susceptible to chemically induced carcinogenesis and chemical toxicity, and mice lacking G6PD exhibit increased renal oxidative stress and are more susceptible to myocardial dysfunction." (PMID 26885667, 2016).
clear cell renal cell carcinoma (7 papers, 2015 to 2025). "Clear cell renal cell carcinoma (ccRCC) is a disease rooted in metabolic disorders, distinguished by abnormally high activity of glucose 6-phosphate dehydrogenase (G6PD)." (PMID 39894218, 2025). "For instance, NF-κB and pSTAT3 synergistically drive G6PD overexpression and facilitate sensitivity to G6PD inhibition in clear-cell renal cell carcinoma." (PMID 35806424, 2022). "Previous results from our laboratory demonstrated that overexpressed G6PD was a potential prognostic biomarker in clear cell renal cell carcinoma (ccRCC), the most common subtype of kidney cancer." (PMID 33041664, 2020). "In addition, G6PD also facilitates clear cell renal cell carcinoma invasion through the ROS−MAPK axis pathway." (PMID 38098504, 2023). "Our recent studies demonstrate that G6PD is significantly higher expressed in advanced status of clear cell renal cell carcinoma (ccRCC) and closely correlates to the tumor extent, lymph node metastasis, Fuhrman grade, TNM stage and poor overall survival of ccRCC." (PMID 29312589, 2017).
heart failure (7 papers, 2012 to 2025). Inability of the heart to pump blood at an adequate rate to meet tissue metabolic requirements. "Supporting this notion up-regulation of G6PD expression and activity has been associated with heart failure, while it has been proposed for a long time that G6PD-derived ribose sugar promotes the development of hypertrophy/compensated heart failure." (PMID 23071515, 2012). "G6PD activity has been shown to maintain cellular glutathione levels and prevent oxidative stress-induced cardiac insufficiency." (PMID 38987688, 2024). "Similar effects were observed in pacing-induced heart failure where inhibition of G6PD activity abrogated elevations in NADPH levels and ROS production in failing hearts." (PMID 31218894, 2020). "This is evidenced during heart failure: G6PD is known to be upregulated during human heart failure, however inhibition of the oxidative PPP in the failing heart either with or without acute hyperglycemia enhanced glucose oxidation and mitigated oxidative stress." (PMID 41561119, 2025).
Hepatic steatosis (7 papers, 2017 to 2024). Steatosis is a term used to denote lipid accumulation within hepatocytes. "While HFD feeding did not increase ALT and AST in plasma of both genotypes, IPA Tox analysis of the liver HFD dataset shows that fatty liver disease (steatosis) was significantly [activation z-score was −1.88 and -log10 (p-value) was 4.06] inhibited in response to G6PD mutation." (PMID 38876306, 2024). "G6PD can regulate several compounds that affect hepatic steatosis as an upstream regulator as well as metabolic pathways." (PMID 38876306, 2024). "Next, we observed sporadic fatty liver phenotypes in Q140K+/+ males, but not WT animals and found in the same males altered gene expression in markers of fatty liver disease (Pnpla2, p = 0.012; Pnpla3, p = 0.050; and G6pd, p = 0.032, Student’s t-tests)." (PMID 32488095, 2020). "Similarly, in a rat model of high fructose-induced steatohepatitis, nicotinamide mitigates liver steatosis and fibrosis by regulating redox homeostasis through a G6PD-dependent mechanism." (PMID 38836220, 2024). "In addition, in rat fatty hepatocytes, NAM was found to reduce oxidative stress and lipid accumulation in hepatocytes via a reduction in the overexpression of glucose-6-phosphate dehydrogenase, thereby slowing hepatic steatosis." (PMID 35448997, 2022). "It has been shown that DHEA can decrease liver steatosis because it is a noncompetitive inhibitor of glucose-6-phosphate dehydrogenase (G6PD)." (PMID 28335515, 2017).
metabolic syndrome (7 papers, 2014 to 2023). A cluster of metabolic risk factors for CARDIOVASCULAR DISEASES and TYPE 2 DIABETES MELLITUS. "Perhaps more pertinent to the metabolic syndrome onset are our results on an increased activity of the glucose 6-phosphate dehydrogenase, the other reticular enzymes involved in metabolizing G6P." (PMID 25905030, 2014). "On the other hand, Hsp27 phosphorylation plays an important role in the activation of G6PD, and the phosphorylation of G6PD results in a reduction of NADPH, subsequently causing oxidative stress which may lead to metabolic syndromes." (PMID 35387262, 2022). "G6PD deficits can be acquired particularly in patients with metabolic syndrome." (PMID 33669011, 2021). "Furthermore, it will be of interesting to assess XPc therapeutic potential in G6PD-deficient patients as proposed for AG1 and its derivatives as well as in the predisposed metabolic syndrome patients." (PMID 34679753, 2021).
non-spherocytic hemolytic anemia (7 papers, 2009 to 2024). "Class A G6PD variants cause Chronic NonSpherocytic Hemolytic Anemia (CNSHA) with less than 20 % median G6PD activity." (PMID 38533298, 2024). "Fyn-/- mice present a moderate chronic non spherocytic hemolytic anemia, worsened by primaquine mediated oxidative stress, similarly to human subjects with Class I G6PD mutations." (PMID 32863204, 2020). "In G6PD deficient patients, mutations between 380 and 410 aa are grouped in Class I G6PD mutations, characterized by chronic non-spherocytic hemolytic anemia [,9]." (PMID 32863204, 2020). "Mutations in the gene encoding G6PD cause the most common enzymopathy that drives hereditary nonspherocytic hemolytic anemia." (PMID 29072585, 2017).
acute viral hepatitis (6 papers, 2013 to 2025). "G6PD, which induces cancer and promotes cancer progression, was found to be activated by long-term exposure to bile acids, and its absence was shown to induce acute viral hepatitis and lead to liver failure in severe cases." (PMID 36467100, 2022).
cardiomyopathy (6 papers, 2011 to 2020). A disease of the heart muscle or myocardium proper. "In mice reductive stress due to increased NADPH production by the PPP enzyme glucose-6-phosphate dehydrogenase (G6PD) has been shown to be associated with protein aggregation and cardiomyopathy." (PMID 30818813, 2019). "In a mouse model, cardiomyopathy caused by the dominant CryABR120G missense mutation was suppressed by mutation of the gene that encodes glucose 6-phosphate dehydrogenase (G6PD), one of the cell's primary sources of reducing equivalents in the form of NADPH." (PMID 23818860, 2013). "In another study, increased glucose-6-phosphate dehydrogenase expression was sufficient to cause cardiomyopathy in transgenic mice, which may be an additional mechanism underlying αB-R120G-associated cardiomyopathy." (PMID 21445271, 2011). "In a mouse model of cardiomyopathy, there was enhanced activity of G6PD with increased production of NADPH and higher levels of GSH, resulting in protein aggregation." (PMID 28981461, 2017). "Therefore, G6PD activity could be a target for the treatment of R120G CryAB cardiomyopathy and heart failure in humans." (PMID 28981461, 2017).
chronic kidney disease (6 papers, 2014 to 2023). Impairment of the renal function secondary to chronic kidney damage persisting for three or more months. "The reduced activity of G6PD might be explained by the high level of oxidized glutathione (GSSG) which is found to be increased in the plasma of patients with chronic renal failure compared to those with normal renal function." (PMID 25261071, 2014).
diabetic kidney disease (6 papers, 2011 to 2024). Progressive kidney disorder caused by vascular damage to the glomerular capillaries, in patients with diabetes mellitus. "Decreased G6PD activity and its resulting decreased NADPH level have been associated with diabetic kidney disease and altered nitric oxide production." (PMID 34285713, 2021). "However, even with these potential shortcomings, trends toward mesangial expansion were observed in the histological preparations suggestive that the diabetic mice were definitely developing diabetic kidney disease and that linagliptin treatment ameliorated this in mice with normal G6PD levels." (PMID 29979777, 2018). "Hyperglycemia decreases G6PD activity through the activation of protein kinase A (PKA) and increase of intracellular oxidative stress, leading to chronic kidney injury, and diabetic kidney disease (DKD)." (PMID 32582032, 2020). "G6PD activity and accordingly NADPH level was significantly decreased in diabetic nephropathy." (PMID 21235803, 2011).